NRG1 (neuregulin 1)
Diseases named in the same sentence as NRG1 in open-access papers (continued):
Sharing a sentence is not in itself a finding about the gene and the disease.
epilepsy (continued). "The regulation of GluN2B by the NRG1-ErbB4-Src signaling axis highlighted the importance of NRG1-ErbB4 signaling in symptomatic epilepsy pathology, and the pathway we described here may offer more opportunities for anti-epileptic drug research." (PMID 28273943, 2017). "Our results suggest that NRG1-ErbB4 signaling may play an important role in symptomatic epilepsy and that NRG1-ErbB4 signaling may act as a homeostasis modulator that protects the brain from aggravated epileptiform activity." (PMID 28273943, 2017). "In addition, the significant effect of Dingxian pill may be via mediating the Egr3-GABRA4, NRG1-ErbB4, MAPK-ERK-Arc, and cox-2-Pgp signal-pathways, which were associated with epilepsy." (PMID 31011358, 2019). "We found that patients with symptomatic epilepsy showed a remarkable increase in protein levels of NRG1 and ErbB4 in the temporal cortex and a substantial decrease in the phosphorylation levels of Glu2B-pY1472 and Src-pY416, two downstream targets of NRG1-ErbB4 signaling." (PMID 28273943, 2017). "Our study revealed a critical role of the NRG1-ErbB4 signaling pathway in symptomatic epilepsy, which is different from that in primary epilepsy, and we propose that the NRG1-ErbB4 signaling may act as a homeostasis modulator that protects the brain from aggravation of epileptiform activity." (PMID 28273943, 2017). "The negative correlation between NRG1-ErbB4 and the phosphorylation of GluN2B, the increased NRG1/ErbB4 and decreased phosphorylation of GluN2B at Y1472, suggests that the NRG1-ErbB4 pathway may be protective against NMDAR-mediated hyperexcitability in symptomatic epilepsy." (PMID 28273943, 2017). "In addition, NRG1-ErbB4 signaling suppressed phosphorylation of GluN2B at position 1472 by Src kinase, and decreased levels of phosphorylation level of GluN2B and Src were detected in human symptomatic epilepsy tissues." (PMID 28273943, 2017). "The Dingxian pills might interfere with epilepsy as well as cognitive dysfunction through Egr3-GABRA4 signal, NRG1-ErbB4 signal, and ERK-Arc pathway." (PMID 31011358, 2019).
cardiomyopathy (10 papers, 2012 to 2025). A disease of the heart muscle or myocardium proper. "Many studies have shown that NRG-1 can repair the heart in the pathophysiology of atherosclerosis, MI, IR, HF, cardiomyopathy and other CVDs." (PMID 40747492, 2025). "Recombinant NRG-1 improves cardiac functions and survival in various experimental models of cardiomyopathy, including cardiomyopathy due to ischemia." (PMID 22792252, 2012). "We identified further genes that regulate the development of trabeculation (NKX2-5, TBX20, HAND2, NRG1, NOTCH1 and DTNA) and those with evidence of involvement in cardiomyopathies (CRYAB and RIT1 (ARHGEF2))." (PMID 39567769, 2024). "Our data suggested similar dysregulation of these molecular pathways in adult-onset cardiomyopathies with increased BMP6 and NRG1 in EC7 and decreased INHBA." (PMID 35926050, 2022). "Furthermore, human ETV1 variants have been associated with conduction disease, highlighting the potential role of the Nrg1-Etv1 axis in the pathogenesis of LVNC and related cardiomyopathies." (PMID 40558659, 2025). "However, despite its efficacy, NRG1 is not clinically relevant as a therapeutic for cardiomyopathy induced by anti-cancer therapies because of its well-established role in preneoplastic signaling." (PMID 35664762, 2022).
colon carcinoma (10 papers, 2016 to 2024). "The gene with the highest mutation frequency was NRG1, but only 5%, indicating that these LLPS-related model genes are conserved in the progression of colon cancer." (PMID 39749343, 2024). "Other regulators for colon tumor differentiation were identified such as Styl2, Kcnb2, Nrg1, and Mpp5." (PMID 38893159, 2024). "Among them, TDGF, NRG1, and GRP have been demonstrated as prognostic indicators for patients with colon cancer." (PMID 35748788, 2022). "Through lasso regression analysis, we selected seven optimal RNA construction models, namely, AGAP3, NHSL1, ENOPH1, NRG1, SNHG16, hsa-mir-1271-5p, and hsa-mir-26b-5p, to predict the prognosis of patients with colon cancer." (PMID 34692670, 2021).
glioblastoma (9 papers, 2006 to 2025). The most malignant astrocytic tumor (WHO grade IV). "Inhibiting NRG1 signaling also improves glioblastoma cell susceptibility to radiation treatment." (PMID 38523646, 2024). "NRG1 is a prognostic biomarker in glioblastoma, it promotes malignancy by inhibiting autophagy via AKT/mTOR pathway." (PMID 40959099, 2025). "To confirm that NRG1 mRNAs are translated into proteins in myeloid cells, we then performed immunohistochemical staining of NRG1 in human glioblastoma (GBM) tissue which is enriched in bone marrow-derived macrophages." (PMID 39210279, 2024). "Among these proteins we found, Guanylate-binding protein 1 (gbp1) and Pro-neuregulin-1 (nrg1) which are key players in glioblastoma progression." (PMID 34646273, 2021). "In miR-125a-3p transduced cells, the ectopic expression of Nrg1 is able to abrogate most effects of migration inhibition and apoptosis promotion in glioblastoma cells." (PMID 25560389, 2015). "The experimental results indicate that addition of S1P induced overexpression of NRG-1 and uPA (and other genes) in a glioblastoma cell line and increased motility/invasivity." (PMID 16901352, 2006). "Similarly, binding of NRG1 to its receptor ErbB3 on glioblastoma cells has been shown to increase cancer cell survival and invasion via the PI3K/AKT and MEK/ERK pathways." (PMID 38523646, 2024). "When the concentration of NRG1 increases, (overexpressed in high grade glioblastoma), the ErbB3/C23 could be released from the complex and moves to the cytoplasm, with positive effect on cell proliferation." (PMID 35255831, 2022). "Then, Western blot analysis showed that miR125a-3p overexpression could decrease the expression of Nrg1 in the U87 glioblastoma cell line." (PMID 25560389, 2015). "In addition, as a result of a double luciferase assay, we found that miR-125a-3p inhibits Nrg1 expression in glioblastoma cells by binding to the 3’UTR of Nrg1." (PMID 25560389, 2015). "Restored Nrg1 expression could significantly abrogate the effects of miR-125a-3p on invasiveness, apoptosis and the promotion of glioblastoma cells." (PMID 25560389, 2015). "This confirmed that miR-125a-3p may regulate the development of glioblastoma in an Nrg1-dependant manner." (PMID 25560389, 2015). "There is no obvious correlation in relative expression levels of these markers in glioblastoma samples and/or premalignant astrocytic progenitors, with perhaps the exception of NRG1 (HER2 ligand) where expression levels are lower in all samples relative to the diploid H9 APCs." (PMID 20423517, 2010). "Furthermore, an increased expression of Nrg1 could reverse the effects of overexpression of miR-125a-3p on the proliferation, apoptosis and migration of glioblastoma cells." (PMID 25560389, 2015). "Furthermore, we confirmed that the expression of Nrg1 could be down regulated by the overexpression of miR125a-3p in glioblastoma cell lines." (PMID 25560389, 2015). "Neurons, have been shown to alter glioblastoma cell behaviour through the synthesis of BDNF and neuregulin-1 (NRG1)." (PMID 38523646, 2024). "It is tempting to hypothesize that in glioblastoma cell lines U373 MG, S1P induces invasion via cross-talk between pathways that include uPA, MMP-9, NRG-1, and VEGF." (PMID 16901352, 2006). "We found that regulation of uPA, NRG-1 and MMP-9 by S1P could be a key player in the invasion of glioblastoma cells." (PMID 16901352, 2006).
Parkinson disease (9 papers, 2011 to 2025). A progressive degenerative disorder of the central nervous system characterized by loss of dopamine producing neurons in the substantia nigra and the presence of Lewy bodies in the substantia nigra and locus coeruleus. "Reportedly, systemic administration of the ErbB4 ligand neuregulin-1 protected dopaminergic neurons in a mouse model of Parkinson’s disease, and constitutively active neuronal c-Abl overexpression resulted in neurodegeneration." (PMID 23638043, 2013).
peripheral nerve injury (9 papers, 2013 to 2024). Injury to a peripheral nerve. "After peripheral nerve injury, microglial cells are activated by molecular mediators such as neuregulin-1, chemokine (C–C motif) ligand 2, and fractalkine; activated microglial cells in turn release IL-6, IL-1β, and TNF-α to cause painful symptoms." (PMID 36348269, 2022). "Based on these evidences, a number of studies focused on the application of exogenous NRG1 to increase NRG1 levels and improve axonal regeneration, remyelination and functional recovery following peripheral nerve injury." (PMID 32277262, 2020). "The aim of this study was to describe the modulation of the NRG1/ErbB system in skeletal muscle after peripheral nerve injury." (PMID 29568012, 2018). "The present study also showed that TLN enhanced NRG receptor signal intensity through increasing Nrg1 mRNA expression and phosphorylation of ErbB2 at a protein level after peripheral nerve injury in STZ-R." (PMID 24288572, 2013). "Our in vitro analysis shows that soluble NRG1 plays a key role for Schwann cell survival, de-differentiation and demyelination, thus suggesting that in vivo, after peripheral nerve injury, soluble NRG1 release or delivery needs to be limited to the early phases after nerve injury." (PMID 29867349, 2018). "Indeed, NRG1 signaling via the ErbB2 receptor was shown to be involved in microglial proliferation and chemotaxis after peripheral nerve injury." (PMID 29375317, 2017). "Although Nrg-1-induced microgliosis has been associated with neuropathic pain in peripheral nerve injury, our previous studies in rat SCI showed no significant change in pain sensation following Nrg-1 treatment." (PMID 29467001, 2018). "Therefore, this study aimed to generate NRG-1 overexpressed DPSCs via lentiviral transfection and to investigate NRG-1’s effect on DPSCs’ regenerative potential in repairing facial nerve injury, clarifying NRG-1’s function in DPSCs and its role in peripheral nerve injury." (PMID 38355448, 2024).
amyotrophic lateral sclerosis (8 papers, 2016 to 2025). Amyotrophic lateral sclerosis (ALS) is a neurodegenerative disease characterized by progressive muscular paralysis reflecting degeneration of motor neurons in the primary motor cortex, corticospinal tracts, brainstem and spinal cord. "NRG1 has been implicated in pathogenic mechanisms of several neurodegenerative diseases, including amyotrophic lateral sclerosis (ALS)." (PMID 41373580, 2025). "Neuregulin-1 (NRG1) is implicated in both cancer and neurologic diseases such as amyotrophic lateral sclerosis (ALS); however, to date, there has been little cross-field discussion between neurology and oncology in regard to these genes and their functions." (PMID 38369520, 2024). "NRG1–ErbB signaling regulates myelination and has been associated with amyotrophic lateral sclerosis (ALS) pathology." (PMID 41373580, 2025). "The overexpression of Nrg1 in mouse models of amyotrophic lateral sclerosis (ALS) and partial muscle denervation improves functional recovery by enhancing collateral reinnervation sprouting through both Akt and Erk pathways." (PMID 28261057, 2017).
cardiac hypertrophy (8 papers, 2014 to 2025). "For example, nitric oxide (NO) secreted by ECs alleviates cardiac hypertrophy through the NO-sGC-cGMP pathway, while endothelin-1 (ET-1) and neuregulin-1 (NRG-1) secretion promote hypertrophy." (PMID 40940801, 2025). "We found that this NRG1/ErbB4 signaling axis contributes to the development of myocardial hypertrophy during prediabetic cardiac injury." (PMID 40746531, 2025). "For the gene NRG1, we found association with ECG measures of ventricular hypertrophy, but also with urea and fibrinogen." (PMID 25329069, 2014). "After cardiac injury, nrg1 has been shown to be upregulated in epicardial-derived cells of the zebrafish heart and is sufficient to promote cardiomyocyte proliferation and cardiac hypertrophy, indicating a critical role in regeneration." (PMID 38526188, 2024). "The expression of ERBB2 interacting protein ERBB2IP (ERBIN), which is important for ERBB2 stabilization and NRG1 signaling and is considered as a negative modulator of pathological cardiac hypertrophy, was expressed in both cell types, and increased in co-culture hiPS-ECs." (PMID 34422835, 2021).
ischemic stroke (8 papers, 2014 to 2026). A stroke disorder caused by obstruction of blood flow to the brain, due to thrombotic (local blood clot formation) or embolic (due to a blood clot or other material traveling from another site) event. "We then sought to explore the underlying molecular mechanisms of beneficial effects of NRG1-AdMSCs after ischemic stroke." (PMID 31560696, 2019). "Together, these findings highlight therapeutic benefits of NRG1-AdMSCs in ischemic stroke, possibly through the stimulation of NRG1-ErbB4 signaling networks." (PMID 31560696, 2019). "Taken together, our data suggest that NRG1-AdMSCs can provide excellent therapeutic potential in ischemic stroke by activating NRG1-ErbB4 signaling network." (PMID 31560696, 2019). "We then assessed the functional impact of NRG1-AdMSCs transplantation after ischemic stroke using mNSS test." (PMID 31560696, 2019). "Further studies exploring differential molecular mechanisms of AdMSCs and NRG1-AdMSCs after ischemic stroke are warranted." (PMID 31560696, 2019). "In the present study, we demonstrated therapeutic potentials of AdMSCs engineered to produce NRG1 in ischemic stroke." (PMID 31560696, 2019). "Collectively, our findings suggest that NRG1-AdMSCs transplantation after ischemic stroke can activate MAPK and Akt pathways, possibly through the upregulation of the NRG1 receptor, ErbB4." (PMID 31560696, 2019). "Studies are underway to understand the mechanisms by which ETS-1 is regulated following ischemic stroke and how it is affected by NRG1." (PMID 29856744, 2018). "We previously demonstrated that neuregulin-1 (NRG-1) was neuroprotective in rats following ischemic stroke." (PMID 27596278, 2016). "Using Conserved Transcription Factor-Binding Site Finder (CONFAC) software, we performed computational analysis to predict transcriptional regulators of genes that were induced following ischemic stroke but were downregulated by NRG-1." (PMID 27596278, 2016). "NRG-1 has been shown to be neuroprotective and reduce inflammation in experimental models of ischemic stroke and neuroinflammation; however, the molecular mechanism involved remains to be elucidated." (PMID 27596278, 2016). "At 1 d after ischemic stroke that was induced by the occlusion of middle cerebral artery (MCAo) for 60 min in Sprague Dawley (SD) rats, adenoviral NRG1, AdMSCs, NRG1-AdMSCs, or PBS were injected into the striatum and serial neurologic examinations were performed." (PMID 31560696, 2019). "NRG1 administration itself could improve neurological outcome in ischemic stroke, implying additional therapeutic effects if MSCs can produce NRG1 more efficiently." (PMID 31560696, 2019). "To capture the mechanisms involved in the initial stages of neuronal injury that occurs in the penumbra, we identified gene expression profiles altered following NRG1 treatment at 3 hours following ischemic stroke and the transcription factors that regulated the expression of these genes." (PMID 29856744, 2018). "We previously showed that neuregulin-1 (NRG1) was neuroprotective in rat models of ischemic stroke." (PMID 29856744, 2018). "Previous studies indicate NRG-1 reduces the expression of ICAM-1 following ischemic stroke." (PMID 24433482, 2014). "Therefore, we engineered AdMSCs to boost NRG1 secretion by adenoviral infection and investigated whether these NRG1-modified AdMSCs (NRG1-AdMSCs) could have better therapeutic potentials after ischemic stroke in rats." (PMID 31560696, 2019). "Transplantation of NRG1-expressing AdMSCs into the ipsilateral striatum after ischemic stroke significantly reduced the brain infarct size and enhanced functional recovery, which was accompanied with the upregulation of both exogenous and endogenous NRG1 expression." (PMID 31560696, 2019).
mucinous adenocarcinoma (8 papers, 2016 to 2025). An invasive adenocarcinoma composed of malignant glandular cells which contain intracytoplasmic mucin. "NRG1 rearrangements accounted for a large portion of Invasive Mucinous Adenocarcinoma (IMA) of the lung of Asian patients, both in KRAS-wild type and KRAS mutated tumors." (PMID 29515761, 2018). "NRG1 fusions were recently reported as a new molecular feature of Invasive Mucinous Adenocarcinoma (IMA) of the lung." (PMID 29515761, 2018). "ALK rearrangement was detected just in one non-mucinous adenocarcinoma (data not shown) without coexisting NRG1 fusions." (PMID 29515761, 2018). "NRG1 gene fusion, which has been reported in KRAS wild-type mucinous adenocarcinomas, was not examined in the present study." (PMID 38710944, 2025).
Obesity (8 papers, 2016 to 2023). Accumulation of substantial excess body fat. "Perturbations in NRG1/ErbB4 function have been associated with various neuropsychiatric disorders, resilience to stress, and obesity/metabolic syndrome." (PMID 35220393, 2022). "Moreover, the NRG‐1/ErbB pathway enhances leptin levels, enlightening the possible approach of exploring underlying mechanisms of action of NRG‐1 in a myocardial IR model with obesity or a high‐fat diet." (PMID 37710187, 2023). "Following the reports indicating that exogenous NRG1 improves metabolic outcomes implicated with obesity, we tested whether exogenous NRG1 administration prevents/delays the onset of obesity symptoms." (PMID 35220393, 2022). "Notably, while ErbB4 deletion predisposes mice to metabolic alterations implicated in obesity, NRG1 administration is known to improve metabolic health in obese mice by lowering blood glucose, improving insulin sensitivity, and reducing caloric intake." (PMID 35220393, 2022). "Consistent with a growing list of studies demonstrating the potential involvement of NRG-ErbB signaling in obesity, we found several significant interactions between the obesogenic diet and exogenous NRG1." (PMID 35220393, 2022). "We showed that exogenous NRG1 administration abolished the obesity-related overproduction of inflammatory cytokines in the hippocampus." (PMID 35220393, 2022). "Recent studies demonstrate that the fibroblast growth factor-21 (FGF21), an hepatokine, is partly responsible for the beneficial actions of an exogenously administered NRG1 fusion protein on obesity-related metabolic outcomes." (PMID 35220393, 2022). "The decrease in Nrg1 expression in DRG neurons of WD-fed mice may suggest an altered Nrg1-dependent neuron-SC communication in Obesity." (PMID 32286429, 2020). "We also evaluated whether BD or obesity is contributing to the NRG1 increase." (PMID 35625715, 2022). "Finally, high-fat diet females exhibited altered mRNA levels of ERBB4 and NRG1, suggesting that obesity may involve disturbances to mammary gland paracrine circuits that are critical in the control of luminal progenitor function and lactation." (PMID 26926925, 2016). "The present study has also demonstrated that obesity is not related to increasing NRG1 in transplanted livers since NRG1 is not different in steatotic and non-steatotic livers either prior to LT or after the implantation of liver grafts." (PMID 35625715, 2022).